SF3B1 (splicing factor 3b subunit 1)
Diseases named in the same sentence as SF3B1 in open-access papers (continued):
Sharing a sentence is not in itself a finding about the gene and the disease.
tumor (continued). "In the vehicle-treated mice, the tumor-cell-injected horns had substantially higher SF3B1 expression than the corresponding normal horns." (PMID 33040078, 2020). "Typical examples included known or putative tumor suppressors, such as NF1, DICER1, PML, PDS5A, MAP3K7, and PPP2R5A, in which SF3B1 mutation resulted in usage of alternative 3′ splice sites." (PMID 30194306, 2018). "Most UMs harbor one Gq pathway mutation (GNAQ, GNA11, CYSLTR2, or PLCB4), one BSE mutation (BAP1, SF3B1, or EIF1AX), and a few recurrent CNAs, in 100% of tumor cells." (PMID 29317634, 2018). "Anti-SF3B1 antibodies were detected in patient’s sera even at the early tumor stage (T1) or in small size tumor (size < 2 cm)." (PMID 29954402, 2018). "The fact that in UMs these SF3B1 mutations are almost mutually exclusive with BAP1 mutations suggests different pathways in the oncogenesis and/or malignant progression of these neoplasms." (PMID 26769193, 2016). "We identified 1,749 junctions that were significantly differentially used between the SF3B1 mutant and SF3B1 wild-type samples across the three tumor types including 1,330 novel junctions, of which 1,117 are novel 3’SSs (BH-adjusted p < 0.1)." (PMID 25768983, 2015). "It remains unknown about the relationship between our observed SF3B1-K700E–induced inflammation and tumor development." (PMID 39303038, 2024). "SF3B1-K700E has been shown to regulate tumor cell proliferation via other mechanisms." (PMID 39303038, 2024). "However, further research is needed to obtain a better understanding of the mechanisms through which SF3B1 modulators induce anti-proliferative effects in tumor cells." (PMID 38975181, 2024). "Considering the advantages and benefits associated with conducting small molecule screens and their potential in identifying possible SF3B1 modulators targeting tumor cells, we conducted a review of the literature of the four compounds identified as potential modulators in this study." (PMID 38975181, 2024). "Aberrant splicing is a well-known tumorigenic mechanism, and indeed, abnormal splicing patterns have been demonstrated in neoplasms carrying SF3B1 hotspot variants in some, although not all studies." (PMID 38067388, 2023). "The occurrence of mutational hotspots and code shift disorders leads to SF3B1 mutations that are considered gain-of-function or tumor morphology-driven mutations rather than loss-of-function mutations." (PMID 37007111, 2023). "Since splicing deregulation has been reported as a hallmark of PDAC, with SF3B1 being recurrently mutated, we aimed at elucidating the impact of the frequently occurring SF3B1K700E mutation to the pathogenesis of this tumor type." (PMID 37823551, 2023). "Additionally, SF3B1 inhibition has been found to suppress proliferation, migration, apoptosis, and the formation of tumor spheres and colonies, as well as angiogenesis." (PMID 37875914, 2023). "Also of interest are the actionable gene mutations acquired and found in tumor progression within nude mice, such as GNAQ, RAC1, and SF3B1." (PMID 37108696, 2023). "Furthermore, SF3B1 was found to be frequently upregulated in advanced PDAC cases and associated with tumor grade and pladienolide B strongly repressed tumor-related features." (PMID 35406598, 2022). "Furthermore, pharmacological SF3B1 blockade also decreased the expression of key tumor progression markers and critical oncogenic spliceosome components in GBM cells in vitro and in vivo." (PMID 35086552, 2022). "SF3B1 silencing led to a significantly reduced tumor burden and prolonged mouse survival." (PMID 35061527, 2022). "We further examined whether chemical inhibition of SF3B1 activity could suppress tumor growth in vivo." (PMID 35061527, 2022).
tumor (continued). "Pladienolide B treatment also decreased the expression of key tumor progression markers and critical oncogenic spliceosome components [previously found to be correlated with SF3B1 in GBM samples] in both cell lines (respectively) and primary-GBM cell cultures (respectively)." (PMID 35086552, 2022). "Despite this varying tumor cell content and different tissues, hierarchical clustering using DMRs with a FC > 5 showed that UM metastases clustered together with either BAP1 or SF3B1-mutated UM implicating that they showed the same secondary driver signature." (PMID 34997020, 2022). "While not in the initial list of significant genes (q = 0.13), SF3B1 nevertheless exhibited skew toward low-burden tumours with all mutations in non-UV samples being identical (R265H, n = 4)." (PMID 36396655, 2022). "In addition, tumor progression and initiation in response to SF3B1 blockade were examined in two GBM xenograft mouse models." (PMID 35086552, 2022). "Our findings elucidate a mechanism through which mutant SF3B1 promotes tumor progression and may provide a potent molecular therapeutic target for prolactinomas with the SF3B1R625H mutation." (PMID 35039052, 2022). "Analysis of tumour biopsies (n = 63) showed that 61 (97%) had likely loss of one copy of BAP1, 23 (37%) had mutations in the gene encoding GNAQ, 26 (41%) in GNA11, three (5%) in CYSLTR2, one (2%) in PLCB4 and 11 (17%) in SF3B1." (PMID 36229663, 2022). "Specifically, a marked SF3B1 overexpression was found in GBM compared to non-tumor brain tissues (control-tissues) in our cohort (n = 22 and 4, respectively), which was also corroborated in another well-characterized external patient cohort (Rembrandt; n = 219 and 28, respectively)." (PMID 35086552, 2022). "Collectively, these results suggest that SF3B1 K700E mutation leads to the aberrant splicing of PPP2R5A and the increased expression of c‐Myc, which leads to an enhanced Warburg effect and subsequent tumor growth in PDAC." (PMID 33932092, 2021). "SF3B1 was overexpressed in human PDAC and associated with tumor grade and lymph-node involvement." (PMID 34857016, 2021). "We also revealed that the number and type of metastases is irrelevant to the prognostic mutation status of the tumor, showing that both BAP1- and SF3B1-mutated UM can result in solitary and miliary metastases, indicating that other processes lay ground to the different metastatic patterns." (PMID 34771480, 2021). "Genetic silencing of SF3B1 only displayed a tumor‐suppressive effect in a PDAC cell line harboring SF3B1 mutation but not wild‐type SF3B1, suggesting a change‐of‐function of SF3B1 mutation in PDAC." (PMID 33932092, 2021). "Furthermore, SF3B1 mutated UM are most likely to have more than 3 chromosomal structural variants (CSV) per tumor, with 70% of UM with >3 CSV harboring SF3B1 mutations." (PMID 33333932, 2020). "Moreover, spliceosome is considered an attractive therapeutic target in tumor pathologies, and the inhibition of SF3B1 (e.g., using pladienolide-B) has been shown to exert antitumor effects." (PMID 31561558, 2019). "It must be considered whether the changes seen in SF3B1 and EIF1AX are the driver mutation of POM, or a secondary change in the tumour." (PMID 30558566, 2018). "We have previously observed in tumour cells that MDMX protein levels are reduced by suppression of a range of splicing factors but that MDM2 mRNA splicing is selectively sensitive to knockdown of SF3B1." (PMID 29796170, 2018). "A recurrent mutation in SF3B1 (p.R625H) was observed in indolent, but not aggressive, tumours; a mutation in EIF1AX (p.N4S) was detected in one patient with non-aggressive disease." (PMID 30558566, 2018).
tumor (continued). "SF3B1 inhibitors have good pre-clinical anti-tumour activity in model systems." (PMID 29796170, 2018). "It is intriguing to investigate how the dysregulation of SF3B1, via either activation or inhibition, could lead to tumor-specific cell death." (PMID 28198434, 2017). "Of note, in one of the three patients the SF3B1 mutation (c.1900G > A (p.(Val634Ile))) was present in a neoplasm diagnosed as melanocytoma, suggesting that SF3B1 mutations are not necessarily associated with worrisome histology." (PMID 26769193, 2016). "Additional recurrent mutations in SF3B1 occurred at codon 666 (K666Q and K666E) in 9% of mutant tumours (2/23), and non-recurrent mutations included G241*, N626D, A633V, Y765C, and D781E, which were found in 22% (5/23)." (PMID 25424858, 2015). "Our results suggest that SF3B1 mutations are associated with alternative splicing of key genes in ER-positive breast cancer that are independent of tumour type." (PMID 25424858, 2015). "Based on our observations that SF3B1 mutant tumours display a conserved splicing signature, we posited that differential splicing of the downstream targets may drive tumour growth." (PMID 25424858, 2015). "Consistent with this, and with the essential function of splicing in eukaryotic biology, mutations in SF3B1 do not lead to widespread changes in the splicing patterns of tumor cells, as assessed with RNA-Seq." (PMID 23656622, 2013). "Similarly, newer SF3B1-targeting inhibitors have emerged, including the Sudemycin family and H3B-8800, which demonstrate stronger splicing interference and cytotoxicity in tumor cells with comparatively milder effects on normal cells, indicating potential clinical applicability." (PMID 41268214, 2025). "Further mechanistic studies identified that the SF3B1 K700E mutation resulted in aberrant splicing of phosphoprotein phosphatase (PPP) 2R5A and led to an increase in c-Myc expression, which ultimately promoted the Warburg effect and tumor growth in pancreatic ductal adenocarcinoma." (PMID 37097392, 2023). "In addition, splicing factor 3B subunit 1 was detected as a vital splicing factor overexpressing in a variety of tumors, after being blocked, it could attenuate tumor aggressiveness and the expression of oncogenic splice variants, and raise overall survival." (PMID 37520979, 2023). "Similarly, a higher SF3B1 expression was observed in human and mouse classical and mesenchymal GBM (subtypes with poorer survival rate) compared to proneural GBM (subtype with better survival rate) or non-tumor samples, which reinforced the prognostic value and potential oncogenic role of SF3B1." (PMID 35086552, 2022). "Therefore, the ubiquitous expression of SF3B1 across all intra-tumor cell types/states suggests that SF3B1 might represent a potential and global pharmacological target against all GBM-populations." (PMID 35086552, 2022). "Moreover, PDAC has high levels of expression of SF3B1, and recent studies have demonstrated a positive correlation between expression levels of wildtype (WT) SF3B1 and tumour malignancy, further supporting the search for drugs targeting this key spliceosomal factor." (PMID 35582381, 2021). "The participants with a) the SF3B1 p.K666N and b) SRSF2 p.P95L/TET2 p.I1873T variants, respectively, both had haematological malignancies diagnosed in a closer timeframe after blood draw (exact date unknown) and therefore, tumour cells may have been detected." (PMID 29641532, 2018). "Six PDXs, representing 20.8% of the tumours in this study, harboured druggable somatic mutations, including PIK3CA p.H1047R and KRAS p.A146V in WHIM9, PIK3CA p.H1047R in WHIM16 and WHIM24, PIK3CA p.E545K in WHIM18, PIK3CA p.E542K in WHIM20 and SF3B1 p.K700E in WHIM26." (PMID 28348404, 2017).
tumor (continued). "With progress in understanding the molecular landscape of the tumor and the development of treatments targeting the pathways involving GNAQ/GNA11, BAP1, EIF1AX, SF3B1 mutations and epigenetic mechanisms, in the near future it may be possible to prevent the progression of micrometastases." (PMID 27800275, 2016). "In addition, to directly determine whether the splice pattern detected in SF3B1MUT tumours is dependent on SF3B1 status, we used two isogenic HEK293T cell lines, SF3B1WT and SF3B1K666T obtained by the CRISPR/Cas9 technology." (PMID 26842708, 2016). "Jerantinine A is a novel indole alkaloid with potent anti-tumor cell proliferative activity by inhibiting microtubulin polymerization, upregulating SF3B1 and SF3B3, and inducing G2/M cell cycle arrest and tumor-specific cell death." (PMID 37007111, 2023). "The key finding of our study is that the release of mtDNA from pyroptotic tumor cells is crucial for the activation of macrophages, and we also identified BCL2L2 as a SF3B1 target gene that plays a role in pyroptosis." (PMID 38012150, 2023). "To further analyse the impact of Sf3b1K700E on the tumor suppressive effect of TGF-β, we exposed Sf3b1 WT and Sf3b1K700E KPC tumor organoids to TGF-β1." (PMID 37823551, 2023). "Tumor DNA from a cohort of 100 UM patients from Moorfields Biobank (UK) that had undergone enucleation were sequenced for known UM driver genes (BAP1, SF3B1, EIF1AX, GNAQ, and GNA11)." (PMID 36077643, 2022). "SF3B1 expression was analyzed at single-cell level (GSE131928; n = 5528), which includes tumor microenvironment (TME) and tumor-like cells." (PMID 35086552, 2022). "We also compared the expression level of these SFs in GBM tumor tissues and adjacent normal tissues and found that 7 factors were significantly dysregulated, including HNRNPA1, HNRNPC, HNRPLL, NOVA1, SF3B1, KHDRBS2, and TIA1." (PMID 34326872, 2021). "6p+ Was usually present in 100% of tumor cells in SF3B1-mutant tumors but only in a subclone in EIF1AX-mutant and BAP1-mutant tumors; 8q+ was usually present in 100% of tumor cells in SF3B1-mutant and BAP1-mutant tumors but was rarely present in EIF1AX tumors." (PMID 29317634, 2018). "Mutations in various splicing regulatory factors such as U2AF1, ZRSR2, SRSF2, SF3B1, and RBM10 have been described in multiple tumor types." (PMID 28105922, 2016). "Inhibitors targeting the SF3B complex or its SF3B1 subunit can precisely calibrate the constitutive or selective splicing of precursor mRNA by altering the ability of SF3B1 and PHF5A to recognize different intron branch point sequences, thereby exerting anti-tumor activity." (PMID 40356980, 2025). "We also detected somewhat puzzling hypermethylation and silencing of genes that would be predicted to be oncogenes, rather than tumor suppressors, such as SF3B1, LCK, FOXP1, and FYN." (PMID 39189258, 2024). "We showed that SF3B1 mutant MDS cases tend to have high levels of inflammation, perhaps due to macrophage activation, and thus confers a good prognosis for patients in terms of anti-tumour activity." (PMID 39235452, 2024). "We also detected somewhat puzzling hypermethylation and silencing of genes that would be predicted to be oncogenes, rather than tumor suppressors, such as SF3B1, LCK, FOXP1, FYN50,51." (PMID 38464090, 2024). "Taken together, the results showed that the inhibition of SF3B1 by pladienolide B prevents tumor growth and induces antitumor immunity, but not through the interferon pathway." (PMID 38012150, 2023).
tumor (continued). "In the replication cohort, metabolite abundancies are slightly different in the BAP1 group, with F1-scores of 0.82, 0.59, and 0.59 for patients harboring a BAP1, SF3B1, and EIF1AX-mutated tumor in the negative ion mode, respectively." (PMID 36982149, 2023). "Inhibition of SF3B1 by pladienolide B significantly prevented tumor growth, with no significant weight change in mice." (PMID 38012150, 2023). "Collectively, these observations suggest that BAP1 deletion preferentially suppresses tumor cell invasion of SF3B1‐mutant Mel202 cells, but not the SF3B1 wild‐type OMM2.3 cells, in xenograft zebrafish models." (PMID 34706158, 2022). "Of note, BAP1 deletion failed to further decrease tumor cell dissemination in Mel202 SF3B1 mut‐KO clone, suggesting the inhibitory effect of the co‐occurrence of BAP1 deletion and SF3B1 mutation on invasion." (PMID 34706158, 2022). "As expected, we did not notice any difference in SF3B1 expression between the tumor-cell-injected horns in the vehicle and the PLAD-B-treated mice, indicating that PLAD-B inhibits SF3B1 activity but not expression." (PMID 33040078, 2020). "Over half of MDS and 5–10% of AML patients have underlying mutation of one of the splicing factors, such as SF3B1, SRSF2, U2AF, ZRSR2, LUC7L2, PRPF8 or SF3B1, although it is not uncommon in other tumour types either." (PMID 32772213, 2020). "To determine whether SF3B1 was required for tumor cell migration, we transfected Ishikawa and AN3CA cells with SF3B1 siRNA or control siRNA, confirmed that SF3B1 mRNA expression was efficiently knocked down, and then performed wound-healing scratch assays." (PMID 33040078, 2020). "In the tumor region of the liver tissue of HBx-Tg mice (especially in large tumor region), SF3B1 was increased compared to that of the non-tumor region." (PMID 29954402, 2018). "Importantly, ectopic expression of SF3B1, SF3B3 or JA treatment induced significant tumor-specific cell death accompanied by the accumulation of unspliced pre-mRNAs." (PMID 28198434, 2017). "SF3B1 expression levels were significantly higher in U-87/U-118 MG cells compared with non-tumor brain tissues and were slightly higher, but comparable, in U-87/U-118 MG cells and GBM samples, suggesting that both cell lines were appropriate GBM models to study SF3B1 functional role." (PMID 35086552, 2022). "A strong association between SF3B1 expression and key tumor -markers of development/progression (VEGFA/MKI67/EGFR/CDK4/PDGFRA) was found in GBM (CGGA- and Rembrandt-datasets), but not in the non-tumor samples (Rembrandt-dataset)." (PMID 35086552, 2022). "No tumor presented concomitant variants in GNAQ/GNA11 and in SF3B1 or BAP1." (PMID 34359736, 2021). "Inhibition of SF3B1 differentially affects tumor cells rather than normal cells." (PMID 30401776, 2018). "It is worth noting that SF3B1 also plays a role in polycomb-mediated repression of Hox genes and, therefore, its role in tumor development might be independent of RNA splicing." (PMID 23656622, 2013). "In particular, studies on UM have identified aqueous and vitreous humor as sources of circulating tumor DNA, but no studies have been specifically conducted on GNAQ, BAP1, SF3B1, and EIF1AX related proteins." (PMID 38175637, 2024). "For example, gene expression class, BAP1, SF3B1, EIF1AX, and chromosome 3 status, presence or absence of vasculogenic mimicry, and tumor cell type are all important prognostic factors that were not accounted for herein." (PMID 36398623, 2023). "Specifically, SF3B1-blockade downregulated anti-apoptotic Bcl-xL, while upregulated the pro-apoptotic Bcl-xS, in GBM, both in vitro and in vivo, but not in non-tumor brain cell cultures." (PMID 35086552, 2022). "However, compared with vector control group, there were significantly fewer tumor cells disseminated away from the yolk sac in the Mel202 BAP1 KO cells, indicating the inhibitory effect of BAP1 deletion on invasion in Mel202 cells, which have SF3B1 mutation, but not OMM2.3 cells." (PMID 34706158, 2022).